MMP9 (matrix metallopeptidase 9)
Diseases named in the same sentence as MMP9 in open-access papers (continued):
Sharing a sentence is not in itself a finding about the gene and the disease.
breast carcinoma (continued). "Concomitant with these observations, our study revealed a significant strong agreement between fascin and MMP-9 expressions in breast carcinoma cases." (PMID 24993803, 2014). "The aim of the present study was to assess the effect of the combined detection of serum vascular endothelial growth factor (VEGF) and matrix metalloproteinase-9 (MMP-9) by Luminex multiplexed assays for the diagnosis, treatment and prognosis of breast cancer." (PMID 24944618, 2014). "MMP-9 was overexpressed in breast cancer specimens compared with peritumoral benign breast epithelium and lymph nodes." (PMID 24845596, 2014). "Here, we show that human breast cancer cell-produced MMP-9 is specifically required for invasion in cell culture and for pulmonary metastasis in a mouse orthotopic model of basal-like breast cancer." (PMID 24811362, 2014). "We identified and validated several known metastasis mediators as regulated by MMP9, including Foxq1 and PLAU, as well as the suspected breast cancer susceptibility gene BRIP1." (PMID 24811362, 2014). "Alternatively, HO-1 appears to counteract tumor growth in non-small cell lung carcinoma and in breast cancer it suppresses the invasive capacity of cells via MMP9 down-regulation." (PMID 24961479, 2014). "Taken together, our data indicate that differential expression of MMP-9 reflects the degree of differentiation of breast cancer cells and that its overexpression tightly correlates with the most aggressive subtypes of breast cancers." (PMID 25151367, 2014). "We next ascertained MMP-9 expression in both normal breast tissue and in human breast carcinoma tissue microarrays." (PMID 25151367, 2014). "Our results indicate that MMP-9 is not only differentially expressed in different molecular breast cancer subtypes but also overexpressed in triple-negative and HER2-positive breast cancers." (PMID 25151367, 2014). "While many of the different MMPs expressed in breast cancer are produced by stromal cells MMP-9 is produced mainly by the tumor cells themselves." (PMID 24811362, 2014). "The current study reports for the first time the direct relationship between fascin and MMP-9 expression in breast cancer." (PMID 24993803, 2014). "Previous studies have provided conclusive evidence that MMP-9 is involved in several key processes that contribute to breast cancer development, progression, invasion and metastasis." (PMID 25151367, 2014). "In other human studies, annexin A1 protein acted as a positive regulator of MMP-9 expression, as well as metastatic invasion of breast cancer cells, through activation of NF-κB signaling." (PMID 25504150, 2014). "In the present study, MMP-9 expression was detected in 50.75% of breast carcinoma cases with weak expression in stromal cells." (PMID 24993803, 2014). "Immunohistochemical expression of fascin and MMP-9 was evaluated semi quantitatively in 67 cases of breast carcinoma regarding the percentage of positive cells." (PMID 24993803, 2014). "Overexpression of MMP-9 was present in basal-like breast cancer cell lines CAL85-1, HCC1395, HCC1143, DU4475, HCC1937, MDA-MB-231 and HCC38." (PMID 25151367, 2014). "To further confirm MMP9 as a mediator of ECM1-dependent effects, we treated breast cancer cells with recombinant human MMP9 (rhMMP9)." (PMID 25499743, 2014). "Previous reports demonstrated that S1P induced MMP-9 expression in breast cancer cells and MMP-2 expression in endothelial cells." (PMID 25188412, 2014). "For this purpose, the levels of VEGF and MMP-9 were compared among breast cancer patients, fibroadenoma patients and healthy adults using a lipid-chip based method." (PMID 24944618, 2014). "Lack of expression of lipocalin 2, which is a secreted glycoprotein and involved in MMP-9 stability, delays ErbB2-induced mammary tumor metastasis with a mechanism that involves decreased MMP-9 activity." (PMID 24709902, 2014). "α-mangostin has been demonstrated to be an inhibitory agent for MMP-2 and MMP-9 in lung and breast cancer." (PMID 23833675, 2013).
breast carcinoma (continued). "Breast cancer cells have been demonstrated to be closely associated with the expression of uPA, MMP-2, MMP-9 and VEGF." (PMID 24137293, 2013). "Further evidence that MMP9 is an important downstream mediator of WNT‐5A‐regulated breast cancer cells migration comes from experiments in which we utilized active human rMMP9." (PMID 23727359, 2013). "Inhibiting MMP2 and MMP9 halted the invasion of metastatic breast cancer cells in the embryonic zebrafish." (PMID 24196484, 2013). "These in vivo data were consistent with the in vitro results and confirmed that the silencing of RABEX-5 inhibits breast cancer growth and progression by modulating MMP-9 transcriptional activity." (PMID 23941575, 2013). "In vitro studies have confirmed that the overexpression of MDM2 confers a more aggressive phenotype to breast cancer cell lines, including higher levels of cell motility and invasion, in addition to inducing the expression and activity of MMP9." (PMID 24236052, 2013). "We validated and applied two different MMP-9:TIMP-1 assays and found that both the commercially available ELISA and the PLA reliably quantified the MMP-9:TIMP-1 complex concentration in plasma samples from breast cancer patients." (PMID 24330623, 2013). "The expression level of MMP-9 has been correlated with the level of activated STAT3 in human breast cancer." (PMID 23326564, 2013). "The precision and performance of the MMP-9:TIMP-1 proximity assay was investigated by analysing four breast cancer plasma samples for their levels of MMP-9:TIMP-1 complex and the GFP spike-in." (PMID 24330623, 2013). "In breast cancer high pre-operative serum MMP-9 concentration or MMP-9 activity in plasma have been suggested as prognostic markers indicating poor patient outcome." (PMID 24330623, 2013). "Costunolide further suppressed TNFα-induced NF-κB signaling activation, resulting in a reduced expression of MMP-9, a well-known NF-κB-dependent gene to mediate breast cancer cell growth and metastases." (PMID 23997800, 2013). "Inhibition of MMP-9 expression by bisphosphonates significantly reduces metastasis to bone in a breast cancer model." (PMID 23577028, 2013). "PPARγ and RAR ligands inhibited human breast cancer cells proliferation, cell invasion, MMP-9 activity and up regulation of TIMP-1 expression." (PMID 24098526, 2013). "Taken together, these results lead us to conclude that WNT‐5A‐mediated impaired breast cancer cell migration and invasion is at least in part explained by a reduced release of MMP9." (PMID 23727359, 2013). "Macrophages have already been described as potent protease producers and MMP9 has been found overexpressed in breast cancer and greatly expressed by M2 macrophages." (PMID 23762835, 2013). "We performed gelatin zymography to measure the MMP-2 and MMP-9 activities and Western blot to examine the TIMP-1, TIMP-2, MMP-2 and MMP-9 expressions in breast cancer cells." (PMID 23533649, 2013). "Together, our data provide evidence that astrocyte secreted MMP-2 and MMP-9 partially mediate astrocyte secretome induced breast cancer metastasis to brain." (PMID 24324647, 2013). "The overall intra-variation was 2.5% (range: 0.8-6.8% (median: 1.9%)) (N = 16) for the MMP-9:TIMP-1 measurements in breast cancer plasma, while the inter-variation between plates was 19.9% (range: 11.3-29.2% (median: 19.6%)) (N = 16)." (PMID 24330623, 2013). "We found that MMP-3 was partially involved in astrocyte CM-induced breast cancer cell invasion but to a lesser extent compared with either MMP-2 or MMP-9." (PMID 24324647, 2013). "In breast tumors, gelatinases, MMP-2 and MMP-9 have been shown to play a significant role in growth and metastasis, as their expression is correlated with aggressive forms of breast cancer." (PMID 23536962, 2013). "In this study, immunohistochemical analysis of Twist, MMP-2 and MMP-9 expression was performed on tissue microarrays from 200 breast cancer cases." (PMID 23935727, 2013).
breast carcinoma (continued). "The positive signals of Twist, MMP-2 and MMP-9 protein expression were predominantly located in the cytoplasm and/or nucleus of breast cancer cells." (PMID 23935727, 2013). "The aim of this study was to ascertain the effects of MDM2 expression on the invasive potential of breast cancer cell lines in vitro, in addition to the effects of MMP9 expression." (PMID 24236052, 2013). "High level of MMP-9 expression in breast cancer is positively correlated with enhanced tumor cell invasion and metastasis and with enhanced progression and poorer prognosis." (PMID 23407024, 2013). "This information led us to next investigate the role of MMP9 in WNT‐5A‐impaired breast cancer cell migration and invasion." (PMID 23727359, 2013). "Two previous analyses of expression found MMP9 plasma concentrations were greater in breast cancer cases compared to controls." (PMID 23634849, 2013). "We screened plasma from 465 patients with primary breast cancer for prognostic value of the MMP-9:TIMP-1 complex." (PMID 24330623, 2013). "In this study, we showed for the first time, that the downregulation of MMP-9 in mammary tumors by a novel anti-MMP-9 DNAzyme molecule results in a significant reduction in final tumor volume in the MMTV-PyMT transgenic mouse model of breast cancer." (PMID 23407024, 2013). "The decrease in both expression level and activity of MMP9 in MDA MB468‐5A cells compared to control cells suggests that this gelatinase is involved in WNT‐5A‐modulated breast cancer cell migration and invasion." (PMID 23727359, 2013). "Downregulation of NF-κB inhibits the production of vascular endothelial growth factor, interleukin-8, interleukin-6, and matrix metalloproteinase-9 (MMP9) each of which are implicated in breast cancer." (PMID 23434903, 2013). "RABEX −5 knockdown also attenuated the migration of breast cancer cells via modulation of MMP-9 transcriptional activity." (PMID 23941575, 2013). "The mean level of MMP-9:TIMP-1 measured by ELISA in the 465 breast cancer plasma samples was 3.63 ng/mL (0.11 – 14.77 ng/mL) and the mean level of MMP-9:TIMP-1 measured by PLA in the 465 breast cancer plasma samples was 0.35 nM (0.09 – 3.50 nM)." (PMID 24330623, 2013). "Northern Blot analysis revealed that the level of MMP-2 and MMP-9 mRNA transcript was higher in breast cancer tissue compared to normal breast tissue." (PMID 23874773, 2013). "IHC analysis of the mammary tumors confirmed that AM9D treatment successfully downregulated MMP-9 protein expression." (PMID 23407024, 2013). "We demonstrated that c-Myb regulates the invasive behavior of breast cancer cells in a matrix-dependent manner, possibly via a novel signaling axis causing the deregulation of MMP1, MMP9, and cathepsin D expression." (PMID 22439866, 2012). "In this study, methyl-β-cyclodextrin reduced uPAR and matrix metalloproteinase-9 (MMP-9) colocalization in lipid rafts and inhibited breast carcinoma cell migration and invasion." (PMID 22811918, 2012). "We show here that AngII up-regulates MMP2 and MMP9 gene expression and enzymatic activity in breast cancer cells, in agreement with studies conducted in the gastric cancer cell line MNK-28." (PMID 22536420, 2012). "In this sense, high levels of MMP2, MMP3 and MMP9 proteins have been implicated in several malignancies including oesophageal, renal, head and neck, oral, colorectal, NSCLC, breast carcinomas and melanomas." (PMID 22455335, 2012). "In breast cancer, studies have implicated FOS as a critical member in the activation of MMP-9 by S1P, resulting in enhanced invasiveness and migration of breast cancer cells." (PMID 23369220, 2012). "Elevated plasma levels of MMP-9 have been found in lung cancer, breast cancer and liver cancer during radiotherapy." (PMID 23183822, 2012).
breast carcinoma (continued). "A significant negative correlation was found between NM modulation of Matrigel invasion inhibition and MMP-9 secretion with breast cancer MDA-MB-231 (r= − 0.851) and MCF-7 (r= −0.993) cell lines and with uterine cancer SK-UT-1 cell line (r= −0.910)." (PMID 22736175, 2012). "Both previous reports on spontaneous transgenic breast cancer in a lipocalin-2 knock-out or wild-type background have identified a high-molecular weight form of MMP-9." (PMID 22737251, 2012). "Depletion of LCN2 in colon, gastric, and breast cancer models diminishes MMP-9 activity thereby attenuating invasion." (PMID 23056397, 2012). "In order to investigate MMP9 activity in breast cancer cells, we used gelatine zymography to analyse enzyme activity." (PMID 23185569, 2012). "NM inhibited MMP expression in all cell lines, with complete block of MMP-9 in breast cancer cells at 100 μg/ml and in uterine and cervical cells at 500 μg/ml." (PMID 22736175, 2012). "Preoperative serum levels of lipocalin-2 and MMP-9 were measured in 303 breast cancer patients and 74 healthy controls recruited between 2004 and 2007." (PMID 22640376, 2012). "Stimulation of the B2R induces MMP overexpression and cell migration in a rat astroglial cell line, while the B1R induces release of MMP-2 and MMP-9 in breast cancer cells." (PMID 21729302, 2011). "We have shown that Stat3 regulates expression of MMP-9 in breast cancer and integrin ß6 in prostate cancer which are critical regulators of invasion and migration." (PMID 22140473, 2011). "MMP-9 mediates invasion of mammary carcinoma cells and invasion/angiogenesis of keratocyte tumours by binding to the hyaluronan receptor, CD44." (PMID 21283680, 2011). "MMP-9 positivity was higher in malignant tumors than in adenomas, confirming previous observations in human breast cancer and canine mammary tumors." (PMID 21726449, 2011). "We found that treatment of MDA-MB-231 cells that express endogenous GPR54 with either 10 or 100 nM of Kp-10 increases the secretion of MMP-9, revealing for the first time that Kp-10 signaling via GPR54 in breast cancer cells stimulates the secretion of MMP-9." (PMID 21738726, 2011). "Knockdown of the GPCR scaffolding protein, β-arrestin 2, inhibited Kp-10-induced EGFR transactivation as well as Kp-10 induced invasion of breast cancer cells via modulation of MMP-9 secretion and activity." (PMID 21738726, 2011). "We found that pterostilbene was able to suppress HRG-β1-mediated cell invasion, motility and cell transformation of MCF-7 human breast carcinoma through down-regulation of matrix metalloproteinase-9 (MMP-9) activity and growth inhibition." (PMID 19617202, 2011). "HRG-β1 is known for its ability to promote aggressive and invasive phenotypes of breast carcinoma by elevating the expression of MMP-9 via the MAPK and p38 kinase cascade pathways." (PMID 19617202, 2011). "Several cell-based studies can provide the molecular basis of the axis of HER2 signaling to MMP-9 expression in breast carcinoma." (PMID 19617202, 2011). "In conclusion, we have evaluated the involvement of MMP-2, MT1-MMP, MMP-9 and various TIMPs in canine mammary tumors, with an emphasis on the stromal compartment." (PMID 21726449, 2011). "The activities of both the pro- and activated forms of MMP-2 and MMP-9 were measured by gelatin-zymography of the plasma of fourteen dogs with mammary tumors and three healthy control dogs." (PMID 21726449, 2011). "Our findings suggest that MMP-9, MMP-2 and MT1-MMP, which are synthesized by epithelial cancer cells and cancer-associated fibroblasts, play an important role in malignant canine mammary tumors." (PMID 21726449, 2011). "qRT-PCR analysis revealed a high level of mRNA expression for MMP-9 in both benign and malignant mammary tumors." (PMID 21726449, 2011).
breast carcinoma (continued). "MMP-9 plays important role in the facilitation of tumor invasion and metastasis, and recent evidence has shown that HRG-β1 can stimulate MMP-9 secretion and activation via a transcriptional regulation in human breast cancer cells." (PMID 19617202, 2011). "In our study, we observed that LR disruption by cholesterol depletion reduced levels of uPAR and MMP-9 in breast carcinoma cells as shown by Western blotting and fibrin and gelatin zymography." (PMID 21106094, 2010). "Theses results are consistent with the known mechanisms of MMP-9 expression in human breast cancer cells and astrocytes." (PMID 21092323, 2010). "MMP-9 plasma concentrations for healthy volunteers averaged 169 ng/mL, while breast cancer patients had plasma concentrations averaging 237.8 ng/mL and colorectal cancer patients averaged 370.1 ng/mL." (PMID 20445741, 2010). "In the present study, we demonstrate that cholesterol depletion by MβCD lowers the surface expression of uPAR and MMP-9 in breast carcinoma cells." (PMID 21106094, 2010). "For examples, Gram-positive bacterium Listeria monocytogene accelerated mouse hepatocarcinoma cell H22 growth via TLR2 signaling; TLR9 agonist CpG ODN promotes breast cancer cell MDA-MB-231 to activation of invasion via increased MMP9 secretion." (PMID 20520770, 2010). "Our results show the implications of cholesterol depletion in uPAR and MMP-9-related cancer cell functions and provide a biological basis for targeting lipid rafts in future breast cancer therapy and treatment." (PMID 21106094, 2010). "Although we would expect to see a decrease in caspase-3 (leading to reduced apoptosis in the KO mammary carcinomas), we were surprised to observe the apparent decrease in mmp-9, and higher expressions of antioxidant genes." (PMID 20932318, 2010). "These include apparent decreases in caspase-3 and mmp-9, but increases in cadherin 1, thioredoxin reductase 2, and glutathione peroxidase 3 in the KO mammary carcinomas." (PMID 20932318, 2010). "As uPAR and MMP-9 are known to be associated with cholesterol-enriched lipid rafts, the present study investigated the effects of cholesterol depletion-mediated lipid raft disruption by MβCD treatment on uPAR and MMP-9 in breast carcinoma cells." (PMID 21106094, 2010). "We have demonstrated that STAT3 and AP-1 are important transcriptional regulators of MMP-7 and MMP-9 in human breast cancer cells previously and STAT3 and AP-1 exert transcriptional regulation functions by binding to their respective elements." (PMID 20939893, 2010). "Pellikainen found that in breast cancer, positive MMP9 expression in cancer cells favored patient's survival." (PMID 20534121, 2010). "Previous studies from our lab have shown that bicistronic constructs against uPAR and MMP-9 have significant inhibitory potential against many types of cancer, particularly breast cancer." (PMID 21106094, 2010). "To summarize, intracellular cholesterol depletion by LR disruption downregulates MMP-9 and uPAR levels and uPAR trafficking in breast carcinoma cells." (PMID 21106094, 2010). "Increased expression of MMP9 is usually seen in invasive and metastatic cancers such as colorectal cancer, gastric carcinoma, pancreatic carcinoma, breast cancer, and oral cancer." (PMID 20534121, 2010). "For MMP-9, a higher amount of mRNA was detected in grade 2 breast cancer tissue when compared to grade 3 breast cancer tissue (p = 0,023)." (PMID 19531263, 2009). "A high expression of MMP-9 and -11 in breast cancer tissue was also detected by Northern blot analysis." (PMID 19531263, 2009). "The metastatic phenotype implies multiple changes; in particular co-expression of CXCR4, VEGF-A and MMP-9 is strongly correlated with lymph node metastasis and is a prognostic marker of the metastatic ability of primary breast cancer." (PMID 19226458, 2009).